Y_RNA (Y RNA )
Gene: Miscellaneous RNA gene on chromosome 2 (121,603,073 to 121,603,164, reverse strand). Ensembl gene ENSG00000222467.
Homologues: Orthologues: chimpanzee Y_RNA (100% identical), macaque Y_RNA (96% identical). Paralogues in human: Y_RNA (89% identical), RNY4P9 (88% identical), RNY4 (87% identical), RNY4P25 (87% identical), RNY4P6 (87% identical), Y_RNA (87% identical), RNY4P19 (86% identical), RNY4P7 (86% identical), Y_RNA (86% identical), RNY4P10 (85% identical), RNY4P14 (85% identical), Y_RNA (85% identical), and 94 more.